DDX11L8 (DEAD/H-box helicase 11 like 8 (pseudogene))
Description:
Putative DNA helicase.
Gene: Unprocessed pseudogene on chromosome 12 (12,310 to 13,501, forward strand). Ensembl gene ENSG00000256263.
Subcellular location: Nucleus, nucleolus